CCT3 (chaperonin containing TCP1 subunit 3)
Diseases named in the same sentence as CCT3 in open-access papers (continued):
Sharing a sentence is not in itself a finding about the gene and the disease.
liver cancer (17 papers, 2013 to 2025). An epithelial or non-epithelial malignant neoplasm that arises from the liver. "Nevertheless, a previous study demonstrated that serum CCT3 was a potential biomarker of liver cancer with a better diagnostic capacity than AFP in certain regards." (PMID 35073517, 2022). "CCT3 was elevated in liver cancer, and its higher expression was associated with poorer overall survival." (PMID 31501420, 2019). "Moreover, the inhibition of ferroptosis by CCT3 has been implicated in the development of lung cancer, while its presence can lead to the inhibition of lipid metabolism and the promotion of lipid accumulation in liver cancer." (PMID 39210442, 2024). "Importantly, we have linked CCT3 to YAP; therefore, targeting CCT3 might be effective in treating YAP-associated liver cancer." (PMID 31501420, 2019). "Previous reports revealed that the liver cancer biomarker CCT3 positively regulates YAP protein stability." (PMID 40985618, 2025). "Through the phosphorylation of transcription factors and STAT3, which enter the nucleus of liver cancer cells, CCT3 has an impact on the development of liver cancer in HCC." (PMID 36185198, 2022). "In liver cancer, CCT3 was elevated and co-interacted with the transcriptional co-activator YAP, which is negatively regulated by the Hippo pathway, and transcription factor CP2 (TFCP2), a Hippo-independent oncoprotein in liver cancer." (PMID 35602608, 2022). "Afteroverexpression, we found that LINC00326 but not the liver-specific control lincRNA HULC was coimmunoprecipitated with CCT3 in liver cancer cells." (PMID 35022268, 2022). "Analysis of some recent cancer-driven genes identified CCT3 as a novel biomarker for liver cancer screening and diagnosis." (PMID 36185198, 2022). "Seral-CCT3 was increased in liver cancer patients compared to normal patients and correlated with other serum markers like alpha-fetoprotein (AFP)." (PMID 35602608, 2022). "In contrast, LINC00326 abundance was low in tumour tissues but increased after the CCT3-KD in liver cancer cell lines." (PMID 35022268, 2022). "CCT3 has been shown to be overexpressed in breast and liver cancers, and its expression level is inversely correlated with the patient survival rate." (PMID 34612768, 2021). "Seral-CCT3 (sCCT3) was specifically elevated in liver cancer compared to that in healthy individuals, hepatitis B (HB), HC, and cirrhosis." (PMID 31501420, 2019). "The diagnostic capability of CCT3 is superior to alpha-fetoprotein to some extent, and targeting CCT3 may be an effective treatment for YAP-related liver cancer." (PMID 39928781, 2025). "Furthermore, silencing CCT3 increases the sensitivity of liver cancer cells to vincristine (a microtubule destabilizer) while decreasing their sensitivity to paclitaxel (a microtubule stabilizer)." (PMID 39928781, 2025). "Increased expression of CCT3 has been associated with unfavorable prognoses in patients with HCC, while its depletion has been shown to induce apoptosis and impede the proliferation of liver cancer cells." (PMID 39210442, 2024). "CCT3 shows high expression in liver cancer, and leads to short survival." (PMID 34414037, 2021). "Here, inhibiting CCT3 has been proven to impair transformative phenotypes in liver cancer cells." (PMID 31501420, 2019). "CCT3 is a potential therapeutic target, and seral-CCT3 might be a promising biomarker for liver cancer screening and diagnosis." (PMID 31501420, 2019). "Importantly, CCT3 can also be regarded as a potential therapeutic target and serum biomarker, thus providing new ways to treat and diagnose liver cancer." (PMID 31501420, 2019). "Inhibiting CCT3 resulted in a suppressed transformative phenotype in liver cancer cells, suggesting that CCT3 might be a potential therapeutic target." (PMID 31501420, 2019). "CCT3 over-expression is also reported to be related to colorectal cancer and liver cancer." (PMID 24278370, 2013).
liver cancer (continued). "Research: Liver cancerAchievement: CCT3 might represent a promising biomarker for liver cancer." (PMID 36185198, 2022). "Together, the CCT3-YAP-TFCP2-PCBP2 axis might be critical for tumourigenesis in liver cancer." (PMID 31501420, 2019). "CCT3 functioned as a trigger of YAP and TFCP2 to affect tumorigenesis and served as a potential biomarker in liver cancer." (PMID 33815471, 2021). "Taken together, in this paper, CCT3 has been identified as an upstream trigger to increase the protein stability of YAP and TFCP2 in liver cancer cells." (PMID 31501420, 2019). "We found that the true positive rate of liver cancer can be increased by the combined usage of previously discovered CD166 and MCAM, current identified CCT3 and traditional AFP." (PMID 31501420, 2019). "Together, CCT3 acts as a trigger of YAP and TFCP2 to affect tumourigenesis and serves as a potential therapeutic target and biomarker in liver cancer." (PMID 31501420, 2019). "It is also worth noting that 15.4–30.6% of patients with liver cancer cannot be well diagnosed even when CD166, MCAM, CCT3 and AFP were combined used, this led us to discover more useful biomarkers to overcome this problem." (PMID 31501420, 2019). "Additionally, CCT3 can also function independently by interacting with YAP and TFCP2 in liver cancer, thereby preventing the PCBP2-induced ubiquitination of these proteins." (PMID 39210442, 2024). "Here, we tested whether the relationship among CCT3, YAP, TFCP2 and PCBP2 is functional in maintaining transformative phenotypes in liver cancer cells." (PMID 31501420, 2019). "We also analyzed the complementary properties of using CCT3 and IQGAP3 in combination with AFP for the diagnosis of HCC, using a logistic regression model,with “0” represents the cirrhosis group, “1” represents liver cancer." (PMID 27390551, 2016). "Spearman’s rank correlation coefficient analysis was then performed according to the IRS to analyse the data from 167 tumour specimens, and significant correlations among YAP, CCT3 and TFCP2 were revealed, suggesting that the CCT3-YAP-TFCP2 loop might be important in liver cancer." (PMID 31501420, 2019).
gastric cancer (10 papers, 2017 to 2025). A primary or metastatic malignant neoplasm involving the stomach. "Our current study in CCT3 and associated pathways might provide information useful for future investigation of molecular mechanism of gastric cancer." (PMID 29340068, 2017). "CCT3 augments the viability of gastric cancer cells by modulating cell cycle proteins, including mitogen-activated protein kinase 7, cyclin D3, and cyclin-dependent kinases." (PMID 35773623, 2022). "Cellular knockdown of CCT3 inhibited proliferation and colony formation, reduced cell viability, and promoted apoptosis of gastric cancer cells in vitro." (PMID 36185198, 2022). "Depletion of CCT3 in thyroid gland papillary carcinoma cells, TNBC cells, or gastric cancer cells decreased cell cycle progression and caused cell cycle arrest, altering signal transduction pathways that drive cell cycling." (PMID 35602608, 2022). "CCT3 is overexpressed in gastric cancer, and CCT3 knockdown can also suppress the proliferation and induce cell apoptosis in gastric cancer and papillary thyroid carcinoma (PTC)." (PMID 33313411, 2020). "Knockdown of CCT3 inhibited proliferation and colony formation while promoted apoptosis of gastric cancer cells in vitro." (PMID 29340068, 2017). "Further studies to determine specific substrates for CCT3 and the precise function of CCT3 in gastric cancer will help development of new cancer therapies targeting CCT3." (PMID 29340068, 2017). "Gastric cancer cells exhibited lower growth potential in nude mice when CCT3 expression was suppressed." (PMID 29340068, 2017). "In this report, we demonstrated that CCT3 was upregulated in the primary gastric cancer tissues and knockdown of CCT3 expression in the gastric cancer cell lines suppresses cancer cell proliferation and promote apoptosis." (PMID 29340068, 2017). "In current study, expression of CCT3 in gastric cancer tissue was probed and the possible role of CCT3 in gastric cancer was explored in cell culture and xenograft animal models." (PMID 29340068, 2017). "Knockdown of CCT3 protein expression in the gastric cancer lines was also confirmed by Western blotting." (PMID 29340068, 2017). "Our study has demonstrated a critical role of CCT3 in the growth and survival of gastric cancer cells." (PMID 29340068, 2017). "In general, the results above suggested that expression of CCT3 is critical for gastric cancer cell proliferation." (PMID 29340068, 2017). "The expression patterns of CCT3 in the surgical specimens from 26 gastric cancer patients were evaluated using immunohistochemistry methods." (PMID 29340068, 2017). "Now that a decreased CCT3 expression was shown to inhibit proliferation and promote apoptosis in gastric cancer cell lines in vitro, it would be interesting to see if CCT3 knockdown confer any anti-tumor activity in vivo." (PMID 29340068, 2017). "RNA interference was used to knock down the expression of CCT3 in gastric cancer cell lines." (PMID 36185198, 2022). "BRD4, the H3K27ac signal reader, was positively relevant with CCT3 expression in gastric cancer." (PMID 36313331, 2022). "CCT3 was found to be important in the growth and survival of gastric cancer." (PMID 36185198, 2022). "Knockdown of CCT3 in a mouse model of gastric cancer reduced tumor size." (PMID 35602608, 2022). "Previous study suggested that CCT3 was critical for gastric cancer cell growth." (PMID 36313331, 2022). "Knockdown of CCT3 reduces the viability of gastric cancer cells by regulating cell cycle proteins." (PMID 35773623, 2022). "It is possible that CCT3 might play a more specific role in gastric cancer cells other than functioning as a component of TRiC." (PMID 29340068, 2017). "Our results suggested that CCT3 played a critical role in gastric cancer growth and survival." (PMID 29340068, 2017). "However, the role of CCT3 in the development of gastric cancer has yet to be determined." (PMID 29340068, 2017).
gastric cancer (continued). "However, little is known regarding the role of CCT3 in the development of gastric cancer." (PMID 29340068, 2017). "CCT3 knockdown blocked the proliferation of gastric cancer (GC) cells." (PMID 36313331, 2022). "used immunohistochemistry to show that CCT3 expression levels were found to be higher in surgical specimens from 26 gastric cancer patients than in non-cancerous epithelial tissue adjacent to cancer." (PMID 36185198, 2022). "In gastric cancer, a higher level of CCT3 expression was detected in tumour tissues than in non-cancerous epithelial tissues." (PMID 32518527, 2020). "Higher level of CCT3 expression was detected in the gastric cancer tissue compared to adjacent non-cancerous epithelium." (PMID 29340068, 2017). "In gastric cancer, CCT3 is highly expressed in the cancer tissues compared with normal tissues." (PMID 35773623, 2022).
lung carcinoma (10 papers, 2021 to 2025). "Although CCT3 has been found to be closely related to the tumorigenesis and progression of various cancers, its potential role in drug resistance of lung cancer and the underlying mechanisms remain unclear." (PMID 34612768, 2021). "In this study, we showed that CCT3 was upregulated in lung cancer tissues based on TCGA database and our qRT-PCR and immunoblotting analysis." (PMID 35773623, 2022). "For example, CCT3 overexpression promoted lung cancer cell growth and migration through regulating YAP1." (PMID 35773623, 2022). "Then lung cancer and paired adjacent normal tissues were collected for the examination of CCT3 mRNA and protein abundance." (PMID 35773623, 2022). "The results showed that CCT3 was highly expressed in lung cancer cells, including H2228, H1299 and H1975, as compared with normal cells Beas-2B." (PMID 35773623, 2022). "In another study, the results showed that CCT3 knockdown induced cell apoptosis in lung cancer cells and promotes the sensitivity of cisplatin on A549 cells." (PMID 35773623, 2022). "Even though two studies have illustrated the function of CCT3 in lung cancer, the precise role and molecular mechanism of CCT3 in LUAD needs more experiments to be determined." (PMID 35773623, 2022). "CCT3 was also upregulated in lung cancer cells compared with lung epithelial cells." (PMID 35773623, 2022). "We found that CCT3 was highly expressed in lung cancer tissues." (PMID 35773623, 2022). "Recently, two articles reported the function of CCT3 in lung cancer." (PMID 35409343, 2022). "Importantly, AKT inhibitor, MK2206, significantly suppressed the growth in CCT3 highly expressed lung cancer cells." (PMID 35773623, 2022). "Recently, the role of CCT3 in lung cancer has been addressed." (PMID 35773623, 2022). "Overexpression of CCT3 promotes the proliferation and growth of lung cancer cells." (PMID 35773623, 2022). "To explore the role of CCT3 in lung cancer, we first analyzed CCT3 based on TCGA database." (PMID 35773623, 2022). "Taken together, we propose that the JAK2/STAT3 pathway may be responsible for the CCT3-mediated cisplatin resistance in lung cancers." (PMID 34612768, 2021). "Furthermore, existing research has demonstrated that CCT3 exerts inhibitory effects on apoptosis, while simultaneously promoting cell proliferation and metastasis in various malignant tumors, including breast cancer, melanoma, and lung cancer." (PMID 39210442, 2024). "Numerous studies have examined the role of CCTs, such as CCT3, CCT5, and CCT6A, in lung cancer, particularly NSCLC." (PMID 39259093, 2024). "Herein, we explored the prognostic value of CCT3 by analyzing the expression of CCT3 in LUAD and LUSC tissues and its correlation with the prognosis of lung cancer patients." (PMID 35773623, 2022). "Our study not only indicates that CCT3 activates AKT to promotes LUAD, but also shows that CCT3 expression level is important for efficacy of AKT inhibitors in lung cancer cells." (PMID 35773623, 2022). "Therefore, targeting AKT may be effective for lung cancer patients with highly expressed CCT3." (PMID 35773623, 2022).
lung adenocarcinoma (8 papers, 2021 to 2025). A carcinoma that arises from the lung and is characterized by the presence of malignant glandular epithelial cells. "Chaperonin containing TCP1 subunit 3 (CCT3) acts as an oncogene in cancers, whereas its role and underlying mechanisms in lung adenocarcinoma (LUAD) are poorly understood." (PMID 35773623, 2022). "In lung adenocarcinoma, knockdown of CCT3 was found to inhibit tumour growth and metastasis by decreasing the amount of intracellular ATP produced via glycolysis." (PMID 38363102, 2024). "Chaperonin-containing tailless complex polypeptide 1 (TCP1) subunit 3 (CCT3) has tumor-promoting effects in lung adenocarcinoma (LUAD)." (PMID 36918801, 2023). "Investigations according to the GEPIA (Gene Expression Profiling Interactive Analysis) web portal demonstrated that CCT3 expression levels were significantly upregulated in both lung adenocarcinoma (LUAD) and lung squamous cell carcinoma (LUSC) tissues." (PMID 36185198, 2022). "Under cisplatin treatment, cell cycle protein B1 and CDK1 protein levels in lung adenocarcinoma cells were significantly reduced after CCT3 knockdown." (PMID 36185198, 2022). "To investigate the role of CCT3 in lung adenocarcinoma growth in vivo, we knocked down CCT3 via lentiviral vectors expressing short hairpin RNA (shRNA) targeting CCT3 in H1299 and A549 cell lines." (PMID 35409343, 2022). "We found that CCT3 was significantly upregulated in lung adenocarcinoma (LUAD) and lung squamous cell carcinoma (LUSC) tissues." (PMID 35773623, 2022). "Research: Lung adenocarcinoma (LUAD)Achievement: CCT3 promote cisplatin resistance of lung adenocarcinoma (LUAD) cells through the JAK2/STAT3 pathway." (PMID 36185198, 2022). "Suppression of CCT3 inhibited tumor progression through the impairment of ATP production and cytoplasmic translation in lung adenocarcinoma." (PMID 35804895, 2022). "In the present study, we aimed to investigate the role of CCT3 in cisplatin resistance of lung adenocarcinoma (LUAD) cells." (PMID 34612768, 2021). "The increased expression of CCT3 in lung adenocarcinoma may lead to uncontrolled cell proliferation by promoting the expression of cyclin B1/CDK1 and thus accelerating cell cycle progression." (PMID 36185198, 2022). "We demonstrated that CCT3 could promote cisplatin resistance of lung adenocarcinoma (LUAD) cells through the JAK2/STAT3 pathway." (PMID 34612768, 2021). "In addition, CCT3 downregulation could sensitize lung adenocarcinoma cells to cisplatin by inhibiting the Janus kinase 2/signal transducer and activator of the transcription 3 (JAK2/STAT3) pathway." (PMID 36185198, 2022).
papillary thyroid carcinoma (8 papers, 2020 to 2023). "The group also showed that AuNPs reduced CCT3 mRNA expression in the papillary thyroid cancer cells, which further demonstrated their antitumor effects." (PMID 36986725, 2023). "Silencing CCT3 inhibited the proliferation, stopped cell cycle and induced apoptosis in papillary thyroid carcinoma cells." (PMID 34505628, 2021). "In papillary thyroid carcinoma, knockdown of CCT3 decreased the proliferation and cell cycle progression and induced the apoptosis of K1 cells." (PMID 32518527, 2020). "Furthermore, CCT3 was closely related to the proliferation and migration of BCa and papillary thyroid carcinoma (PTC)." (PMID 33815471, 2021). "In addition, CCT3 is also overexpressed in papillary thyroid carcinoma (PTC) specimens." (PMID 35773623, 2022). "In papillary thyroid carcinoma (PTC), CCT3 was also upregulated and its knockdown significantly suppressed the proliferation of PTC cells." (PMID 34612768, 2021).
cholangiocarcinoma (6 papers, 2016 to 2023). A carcinoma that arises from the intrahepatic biliary tree (intrahepatic cholangiocarcinoma) or from the junction, or adjacent to the junction, of the right and left hepatic ducts (hilar cholangiocarcinoma). "The maximal log2 fold change (tumor vs. normal) of CCT3 mRNA expression was observed in cholangiocarcinoma (CHOL, 29.6), and that of LUAD was 27.5." (PMID 36918801, 2023). "The maximal log2 fold change (tumor vs. normal) of CCT3 expression was observed in cholangiocarcinoma (CHOL, 29.6), and that of LUAD was 27.5." (PMID 36918801, 2023). "Research: CholangiocarcinomaAchievement: CCT3 is a potential biomarker for cholangiocarcinoma (CCA)." (PMID 36185198, 2022). "The proteomic-based study shows that patients with cholangiocarcinoma (CCA) which are positive for CCT3 and CCT3 might be potential biomarker for the diagnosis of CCA." (PMID 27818681, 2016).
multiple myeloma (6 papers, 2020 to 2025). "In multiple myeloma, CCT3 was also a significant indicator of poor prognosis, and CCT3 expression was associated with the JAK-STAT3 pathway, Hippo signalling pathway, and WNT signalling pathway." (PMID 32518527, 2020). "Moreover, its expression also exhibits prognostic significance in multiple myeloma, enabling the better risk stratification of stage II myeloma patients, underscoring the translational value of circ-CCT3 for precision oncology in solid and hematological malignancies." (PMID 41153715, 2025). "In multiple myeloma, circ-CCT3 binds miR-223-3p, attenuating the miR-223-3p-mediated repression of bromodomain containing 4 (BRD4) to sensitize cells to bortezomib treatment." (PMID 41153715, 2025). "First, bioinformatic analyses of multiple myeloma identified CCT3 targeted genes that were involved in the JAK/STAT3 pathway." (PMID 34612768, 2021). "Furthermore, it has been reported that increased expression level of CCT3 predicted the progression and adverse outcomes of multiple myeloma patients." (PMID 34612768, 2021). "For instance, a bioinformatics study showed that CCT3 overexpression might affect the progression of multiple myeloma through the JAK/STAT3 pathway." (PMID 34612768, 2021).